CXCR4 (C-X-C motif chemokine receptor 4)
Diseases named in the same sentence as CXCR4 in open-access papers (continued):
Sharing a sentence is not in itself a finding about the gene and the disease.
tumor (continued). "Tumor cells expressing CXCR4 that detach from the primary tumor and enter the circulatory system can migrate toward organs that express its ligand CXCL12." (PMID 28191313, 2017). "For the overall study population, baseline CXCR4 expression in tumor tissue positively correlated with baseline %CXCR4+ CTCs (r = 0.423, 95% CI = 0.174, 0.616; P = 0.001)." (PMID 28299514, 2017). "On the contrary, we found a tendency towards a higher grafting capability for tumours according to the presence of CD133+/CXCR4+/EpCAM− cells." (PMID 28751748, 2017). "In NSCLC tumor cells resistant to the EGFR TKI gefitinib the expression of CXCR4 maintains stemness through JAK/STAT3 downstream signaling." (PMID 28402937, 2017). "Treating the cells with HT-EA reverted the forced expression-induced cell migrations, demonstrating that HT-EA deters tumor cell migration by selectively targeting radiation-induced CXCR4 and COX2." (PMID 27974694, 2017). "Elevated expression of CXCR4 has been observed in more than 20 different human tumor types, and the level of CXCR4 expression was associated with tumor grade and poor prognosis." (PMID 27896627, 2017). "In order to further demonstrate the role of CXCR4 in the invasion and metastasis of ECSCs, we established a mouse caudal vein tumor xenograft model." (PMID 28193907, 2017). "A strong expression of CXCR4 on tumor vessels has already been shown for other tumor entities and, hence, targeting of these vessels via CXCR4 has already been suggested as a novel cancer therapy." (PMID 29163802, 2017). "Deletion of Cxcl12 in endothelial cells or pharmacological blockade of Cxcr4 inhibits antral tumor growth." (PMID 29340033, 2017). "As it is known to all, CXCL12/CXCR4 plays an important role in maintaining tumor invasion and metastasis." (PMID 28193907, 2017). "Mechanistic studies implied that PEG-PE micelle can encapsulate E5 and improve E5 targeting efficiency for CXCR4 by accumulating E5 on the tumor cell membrane." (PMID 28793338, 2017). "In many cases including our research, the most expected effect of CXCR4 antagonist is to increase the sensitivity of tumor cells to therapeutics by blocking CXCR4, instead of killing cells directly." (PMID 29263923, 2017). "C-X-C chemokine receptor type 4 (CXCR4) is a member of the G protein-coupled seven-transmembrane receptors (GPCRs), which is expressed lower in normal tissues but significantly higher in tumor tissues." (PMID 28969092, 2017). "Recent studies have determined that the biological functions of CD26 are related to metastatic capacity in colorectal CSCs,10, 11 while CXCR4 is regarded as a key receptor that is closely involved in tumor invasion and metastasis." (PMID 27524415, 2017). "Only four tumor samples (6% of the cases) displayed moderately strong CXCR4 expression with an IRS value ≥6." (PMID 29282035, 2017). "Our analyses represent the first report we are aware of measuring CXCR4 expression in both tumor and CTCs, using the CELLSEARCH® platform." (PMID 28299514, 2017). "Interaction of SDF-1/CXCR4 plays an important role in tumor cell proliferation, survival, invasion, metastasis, and immune suppression." (PMID 29212254, 2017). "Consistently, Nef-M1 peptide, a peptide antagonist of CXCR4, inhibits tumor EMT process by targeting CXCR4." (PMID 28415580, 2017). "We showed that E5 improved the efficacy of multiple chemotherapeutics in mice bearing breast cancer tumors (4T1) by inhibiting tumor angiogenesis and tumor cell adhesion to stromal cells by blocking the CXCR4/CXCL12 axis." (PMID 29263923, 2017). "Galectin-1 was also recently shown to promote tumor progression through upregulation of CXCR4 via activation of the NF-κB pathway." (PMID 29156810, 2017). "Recent studies have indicated an important role for the CXC chemokine receptor (CXCR4) in regulating the expression of genes involved in tumor progression, angiogenesis, and the metastasis of tumor cells." (PMID 29117108, 2017).
tumor (continued). "To assess the contribution of Cxcr4+ ILCs in antral tumor development, we treated MNU-treated mice with an anti-CD90.2 antibody." (PMID 29340033, 2017). "It has been suggested that CXCR4 expression by tumor cells, plays a critical role in cell metastasis by a chemotactic gradient to organs expressing the ligand SDF-1." (PMID 28279221, 2017). "Although CXCR4 is a membrane receptor, its intracellular segregation following CXCL12 stimulation has been widely reported and associated with high tumor malignancy." (PMID 28186979, 2017). "More recently, the CXCL12/CXCR4 axis was reported to be involved in mediating tumour cell invasion and proliferation and to play an important role in tumour angiogenesis, progression, and metastasis." (PMID 28386296, 2017). "In particular, the SDF-1/CXCR4 axis, which was demonstrated by many recent studies, plays a crucial role in tumor–stromal interactions." (PMID 29254283, 2017). "In tumor cells expressing a high level of CXCR4, the disruption of the CXCR4-CXCL2 interaction induces a diminution of the interactions of cancer cells with the bone marrow environment." (PMID 28635657, 2017). "Our quantification of differences in CXCR4 expression in multiple tumor nodules in a single patient at one time offered a good opportunity to assess potential biological correlates of CXCR4 expression." (PMID 29088715, 2017). "Further disruption of SLIT2 and ROBO1 has been shown to induce SDF1 and CXCR4 shifting the tumor microenvironment in an increased inflammatory state and further promoting invasion." (PMID 28440283, 2017). "It has been suggested that ACKR3 and CXCR4 cooperate in enhancing tumor growth, sometimes through separate effects on cancer cells and angiogenesis, and blocking ACKR3 has been shown to diminish growth of tumors in mouse models." (PMID 29088715, 2017). "One CXCR4-targeting imaging agent has even been studied in a recent clinical trial, indicating the suitability of it to identify tumor cells in patients." (PMID 28549419, 2017). "CXCL12, as one of the CXC chemokines, was previously shown to be involved in chronic inflammation, chemotaxis, and tumor development via its specific receptor CXCR4." (PMID 28938626, 2017). "Firstly, side effects of CXCL12/CXCR4 axis inhibitors upon extra‐tumor tissues or cells exist objectively, although some inhibitors have been clinically approved." (PMID 28544785, 2017). "Organs typical for CXCL12/CXCR4-mediated tumor infiltration, such as bone marrow, brain, lungs and spleens were collected." (PMID 29156704, 2017). "Taking together, the data suggested that QRHX inhibited tumor cell-TAMs interactions possibly through blocking CXCL12/CXCR4/JAK2/STAT3 signaling pathways and then regulated macrophages polarization." (PMID 28630636, 2017). "The critical role of CXCR4 in influencing every stage of metastasis, including tumor cell migration, growth, invasion, and angiogenesis, has been recognized." (PMID 27974694, 2017). "The gene expression profiles of MSCs exposed to various tumor cell-derived conditioned mediums revealed the downregulation of matrix metalloproteinase-2 and the upregulation of CXCR4." (PMID 28740515, 2017). "So CXCR4 positive tumour cells move towards the high concentration CXCL12 organs to realize tumour metastasis." (PMID 28403883, 2017). "Compared to NS group, oral administration of QRHX dramatically attenuated the increased expressions of CXCL12 and CXCR4 in tumor tissue (P < 0.01)." (PMID 28630636, 2017). "Treatment in these models with CXCR4 antagonists resulted in selective reduction of intra-tumor regulatory T-cells and concomitant increases in T-cell mediated antitumor immune responses." (PMID 29212254, 2017). "In contrast to HCC, CCCs have not been evaluated for SSTR expression so far and only one study has examined CXCR4 expression in CCC, demonstrating correlations between CXCR4 expression and tumor progression, metastasis, and poor patient outcomes." (PMID 29282035, 2017).
tumor (continued). "The adhesion molecules ICAM-1, VCAM-1, E-selectin and galectin-3 as well as the chemokine system CXCL12/CXCR4 have been reported to be involved in the interaction of tumor and endothelial cells." (PMID 29100413, 2017). "C-X-C motif chemokine receptor 4 (CXCR4) is a key factor for tumor growth and metastasis in several types of human cancer." (PMID 29228566, 2017). "The chemokine receptor CXCR4 represents another promising molecular target structure for tumor diagnosis and therapy." (PMID 29282035, 2017). "The SDF-1α/CXCR4 pathway directly induces HSC differentiation and proliferation by activating MAPK to increase tumor-associated fibrosis." (PMID 28423574, 2017). "When the induction time was prolonged as 4–8 h, the expression level of CXCR4-EGFP increased similarly to native tumor cells." (PMID 29203889, 2017). "Expression of chemokine receptor subtype CXCR4 on tumor cells was demonstrated qualitatively and semiquantitatively by IHC." (PMID 29221153, 2017). "The original view of stromal cell-secreted CXCL12 acting on CXCR4-expressing tumor cells in a paracrine manner has evolved in recent years." (PMID 28055968, 2017). "CXCR4 overexpression in tumor tissue has been correlated to tumor aggressiveness, high risk of metastasis and recurrence." (PMID 28969092, 2017). "It demonstrates that the EMT-promoting signals conveyed by CXCL12 to NET cells are critically sensed by surface CXCR4 leading to transcriptional, structural and functional modifications that culminate in enhanced tumor osteotropism." (PMID 28186979, 2017). "Signaling between SDF-1α and CXCR4 contributes to tumor growth, angiogenesis, invasion and metastases in numerous malignancies." (PMID 28978091, 2017). "The in vivo migration of CXCR4-overexpressing MSCs to MDAMB231/Rluc tumor model by BLI imaging was also confirmed." (PMID 28740515, 2017). "CXCR4 is often expressed in tumor cells with its overexpression associated with poor prognosis in many cancer types, and SDF-1 is highly expressed in tumor microenvironments." (PMID 29212254, 2017). "Most notably, CXCR4 was intensely expressed on the tumor capillaries in about 50% of the HCCs and CCCs." (PMID 29282035, 2017). "More recently, CXCR4 downstream signaling pathways have been shown to contribute to cancer progression by supporting the proliferation and survival of tumor cells and promoting tumor-related angiogenesis and metastasis of various types of human cancer." (PMID 28410420, 2017). "In breast cancer, ACKR3 expressed in trans can modulate CXCL12 levels leading to altered CXCR4-dependent tumor growth." (PMID 29156704, 2017). "AMD3100 significantly reduced the number of Cxcr4+ epithelial cells in the gastric antrum and decreased macroscopic tumor size." (PMID 29340033, 2017). "In the glioblastoma model specifically, decreased GRK3 expression resulted in abnormally sustained CXCR4 signaling and enhanced tumor growth." (PMID 27049755, 2016). "Functionally, CXCR4 plays a role in many phases of tumor biology, including tumor growth, survival, invasion, and metastasis." (PMID 26954567, 2016). "It is noteworthy that, at the end point, the number of CD133 and CXCR4 positive cells in this tumor population was two folds that in xenografts induced by rhabdospheres." (PMID 26897742, 2016). "It is thus important to investigate if KLF8 plays a role in tumor angiogenesis and resistance to anti-cancer therapies such as radiotherapy and if CXCR4 is involved." (PMID 26993780, 2016). "TGFβ has cell compartment-specific autocrine and paracrine effects, it contributes to tumour cell proliferation by up-regulating CXCR4 in epithelial cells, and enhancing invasion." (PMID 27563925, 2016). "Knockdown of HIF2α abrogated CXCR4 expression and sphere formation, while inhibition of HIF2α abolished tumor growth in vivo, revealing the crucial role of HIF2α activation in CSC expansion." (PMID 27293448, 2016).
tumor (continued). "Numerous studies show that an elevated CXCR4 expression in tumor samples from RCC patients is correlated with poor outcome." (PMID 27293448, 2016). "The interaction of CXCR12 (SDF-1), secreted by endothelial cells, with tumor cell expressed CXCR4 is sufficient to stimulate transendothelial migration of the tumor cells." (PMID 27901093, 2016). "We used IT1t, a potent CXCR4 antagonist, and show for the first time its promising anti-tumor effects." (PMID 26744352, 2016). "Results obtained from our study suggest that CXCR4-targeted imaging will aid in the development of therapeutic regimens based on the status of tumor CXCR4 expression and towards realizing precision medicine." (PMID 26848769, 2016). "It has also been shown that chemo- radiotherapy induces a CXCR4-dependent angiogenic switch which correlates to tumor recurrence." (PMID 27863376, 2016). "On the other hand, all chemokine receptors in the omental tumor tissues and the parental cells were still in low levels although the increased level of CXCR4 mRNA was observed in SKCXCR2 omental tumor tissues." (PMID 27723802, 2016). "We found that, compared to unsorted control cells, CXCR4+/Lgr5-, Lgr5+/CXCR4- and Lgr5+/CXCR4+ Caco-2 and HT-29 cells generated significantly more tumor spheres." (PMID 27835894, 2016). "We added AMD3100 to block the interaction of CXCL12 with CXCR4 during the LDH release assay while testing B cell cytotoxicity against 4T1 tumor cells." (PMID 27528023, 2016). "CXCR4 chemical inhibition affected tumor burden, with a 39.5% and 60% reduction at 2 and 4 dpi, respectively." (PMID 26744352, 2016). "Clusters of VEGFR1+ HPCs expressing VLA-4, the fibronectin receptor, interact with resident fibroblasts to stimulate fibronectin production and secrete MMP9 to create fitting niches for the recruitment of disseminating CXCR4+ tumor cells." (PMID 28032860, 2016). "In this study, we analysed the relationship between CXCL12/CXCR4 expression and tumor proliferation in patients with ESCC." (PMID 27439769, 2016). "Several studies reveal that N2 neutrophils express MMP9, NE, and CXCR4, among other pro-tumor mediators." (PMID 27169366, 2016). "Together, our in-vivo studies confirmed that CXCR4 down regulated tumor-bearing mice survived longer than the control mice." (PMID 27863376, 2016). "Further, both in vivo and in vitro experiments confirmed the pivotal role of the SDF-1/CXCR4 axis in mediating the promotive effect of EphA1 on EPCs’ homing to tumor neovasculature." (PMID 27066828, 2016). "Using this data, CXCR4 expression was shown to significantly increase in tumor cells compared to normal tissue as previously believed." (PMID 27049755, 2016). "Chemokine receptor CXCR4 is a key factor for tumor growth and metastasis in several types of human cancer." (PMID 26843617, 2016). "It exerts multiple tumor-promoting functions via either its receptor CXCR4, which is expressed on cancer cells and enhances tumor growth and metastasis, or the recruitment of endothelial progenitors for tumor angiogenesis." (PMID 27996037, 2016). "We assumed that the stimulation of SDF-1 can promote tumor cell metastasis, and long-time stimulation can contribute to the down-regulation of CXCR4 in CRCLM." (PMID 27835898, 2016). "In hepatocellular carcinoma cells, the exocyst positions receptors at the PM such as the G-coupled chemokine receptors CXCR4, whose overexpression is known in a range of tumor types, where it plays a central role in tumor growth and metastasis." (PMID 27148529, 2016). "In vitro, CXCR4 inhibition by LY2624587 leads to the cell apoptosis in tumor cells expressing high levels of CXCR4." (PMID 26954567, 2016). "More importantly, RCC samples showed a decreased expression of CXCL12 and increased expression of CXCR4, compared to their respective adjacent normal kidney tissue, revealing a role in tumor progression." (PMID 27293448, 2016).
tumor (continued). "Of note, blockade of FasL and CXCR4 simultaneously inhibited B cell-mediated killing of tumor cells in an additive manner, indicating that both Fas/FasL and CXCR4/CXCL12 axes are involved in the killing of tumor cells by B cells." (PMID 27528023, 2016). "Depending on CXCR4 expression and specific genetic and microenvironment background, SDF-1 and CXCR4 axis appears to be an important survival mechanism in tumor cells." (PMID 26954567, 2016). "The CXCL12/CXCR4 axis forms critical communication bridges between tumor cells and stromal cells to create a permissive microenvironment for tumor growth and metastasis." (PMID 27293448, 2016). "An additional chemokine/receptor axis involved in migration of neutrophils into tumor site is CXCL12/CXCR4 axis." (PMID 28066438, 2016). "In contrast, among cases with cells able to downregulate CXCR4, a majority had tumor burden and shorter time to first treatment (41/57)." (PMID 27127886, 2016). "Chemokine receptor CXCR4 has been described to play a pivotal role in tumor growth and progression, tumor invasiveness and metastasis." (PMID 26843617, 2016). "Corticosterone levels that were below the range observed in cachectic or food-restricted pre-cachectic mice were sufficient to abolish the anti-tumor effect of dual CXCR4 and PD-L1 antagonism in mice bearing autochthonous PDA." (PMID 27829137, 2016). "Treatment of mice bearing chemoresistant primary tumors with the specific CXCR4 inhibitor AMD3100 reduced the growth of the primary tumor by 61% (P<0.05) and additionally suppressed metastasis formation by 43%." (PMID 27835905, 2016). "Negative methylation/expression correlations were also found for HDAC4 (a chromatin modifier), ERBB3 (a known oncogene), as well as MARCKS and CXCR4; genes known to induce tumor cell invasion and therapeutic resistance in other tumor types." (PMID 26963385, 2016). "The high tumor uptake and retention of 89Zr-CXCR4-mAb by CXCR4 overexpressing tumors make this imaging agent a viable tool for in vivo detection of CXCR4 expression." (PMID 26848769, 2016). "Of note, in comparison to [18F]FDG-PET/CT as reference, almost all tumor lesions proved to be CXCR4-positive with high tumor-to-background ratios, thus rendering CXCR4 a promising target for endoradiotherapy." (PMID 26843617, 2016). "Research focusing on the recruitment of MSCs to tumour cells has identified the importance of various signalling molecules in this process, including CXCR4, MCP-1 and VCAM-1, all of which are regulated by NF-κB." (PMID 27542276, 2016). "The main molecules involved in HSC and tumour cell migration are couple chemokine (C–X–C) receptor type 4 (CXCR4) and 6 (CXCR6) and their respective ligands, C–X–C motif chemokine ligand 12 (CXCL12) and 16 (CXCL16)." (PMID 27782035, 2016). "The tumor growth-stimulating role of CXCR4 was confirmed by showing that CXCR4 antagonists inhibit tumor growth in multiple experimental orthotopic, subcutaneous human xenograft, and transgenic mouse models." (PMID 26920352, 2016). "Our results also show a CXCR4-expression dependent therapeutic effect of the CXCR4-mAb for reducing tumor growth in TNBC xenografts." (PMID 26848769, 2016). "We found that Lgr5+/CXCR4+ cells had significantly higher rates of tumor development, compared to others, based on bioluminescence examination." (PMID 27835894, 2016). "Accumulation in tumor is promoted by the N-terminal peptide T22, which is a potent ligand of the cell surface cytokine receptor CXCR4." (PMID 27059706, 2016). "We demonstrate that KLF8 plays a critical role in both invasive growth of the local primary tumor and the lung metastasis in a CXCR4-dependent manner." (PMID 26993780, 2016). "Blocking CXCR4 in vitro impaired tumor mass formation in vivo: few cells remained in the CV at 2 dpi and consequently minor invasive events occurred at 4 dpi." (PMID 26744352, 2016).